DLL4 (delta like canonical Notch ligand 4)
Diseases named in the same sentence as DLL4 in open-access papers (continued):
Sharing a sentence is not in itself a finding about the gene and the disease.
non-squamous non-small cell lung cancer (2 papers, 2017 to 2020). "A phase Ib trial of Demcizumab targeted DLL4 combined with standard chemotherapy resulted in 50% patients with objective tumor response by regulating Notch signaling and angiogenesis in metastatic non-squamous non-small cell lung cancer." (PMID 33425722, 2020). "Demcizumab is a humanized immunoglobulin G2 antibody that binds to Delta-Like Ligand 4 (Drosophila, DLL4), and is being studied in an ongoing phase 1b dose escalation study in combination with pemetrexed and carboplatin in chemotherapy-naïve stage IIIb/IV non-squamous non-small cell lung cancer." (PMID 33959299, 2017).
psoriasis (2 papers, 2020 to 2025). An autoimmune condition characterized by red, well-delineated plaques with silvery scales that are usually on the extensor surfaces and scalp. "DLL1 is the Notch ligand detected in the epidermis, and a previous study demonstrated increased expression of DLL4 in psoriasis lesional skin compared to unaffected skin." (PMID 40018044, 2025). "We considered it likely that DLL4 is expressed also on monocyte-derived cells, which potently activate T cells and induce inflammatory conditions, including psoriasis." (PMID 40018044, 2025). "Thus, we considered it likely that DLL4 is expressed on monocyte-derived cells, which potently activate T cells and induce inflammatory conditions, including psoriasis." (PMID 40018044, 2025). "Nevertheless, it will be intriguing to elucidate the roles of DLL4+ Mo-LCs because DLL4+ Mo-LCs may be responsible for T cell activation in autoinflammatory immune diseases such as psoriasis and may also be efficacious for cancer treatment." (PMID 40018044, 2025). "Additionally, emerging data suggest a relationship between DLL4 and psoriasis." (PMID 40018044, 2025). "Thus, both DLL1 and DLL4 are likely to be detected in psoriasis lesional skin." (PMID 40018044, 2025). "However, DLL1 may be the first Notch ligand to induce Mo-LCs or DLL4 expression given that DLL1 is detected in unaffected skin and DLL4 expression increases in psoriasis lesional skin." (PMID 40018044, 2025). "The results of this study highlighted an increased expression of Notch1, DLL4, Hrt-1 (Ring-box protein HRT1) and A-SAA (Acute-phase Serum Amyloid A) in Psoriasis lesional skin if compared to unaffected skin." (PMID 32545758, 2020).
respiratory syncytial virus infection (2 papers, 2017 to 2023). "In contrast, respiratory syncytial virus infection up-regulated the expression of Dll4 on DCs, resulting in an attenuated Th17 response." (PMID 38004829, 2023).
skin tumors (2 papers, 2017 to 2020). "The comparative gene expression analysis of skin tumors developed by wild-type vs. Dll4 overexpression mice confirmed that Dll4/Notch signaling restricts VEGF dependent neoangiogenesis." (PMID 28288569, 2017).
Stroke (2 papers, 2022). Sudden impairment of blood flow to a part of the brain due to occlusion or rupture of an artery to the brain. "Dll4 upregulation in V-SVZ vascular cells after stroke was accompanied by Notch activation in adjacent proliferating NSPCs and NBs." (PMID 35450289, 2022). "Supporting this hypothesis, stroke caused an upregulation of the Notch ligand Dll4 in endothelial cells and pericytes of V-SVZ blood vessels in vivo, and VEGF treatments promoted Dll4 expression in endothelial cell cultures in vitro." (PMID 35450289, 2022). "To test this, we administered SU5416, a VEGFR2 inhibitor, during the vascular remodeling period after stroke and analyzed VEGFR2 activation and its downstream target Dll4 expression." (PMID 33978913, 2022).
type 1 diabetes (2 papers, 2016 to 2017). "Several studies have demonstrated the importance of DLL4 in the T cell response in multiple diseases including respiratory syncytial virus, experimental autoimmune encephalomyelitis, type 1 diabetes, and the mycobacterial-elicited pulmonary immune response." (PMID 27933064, 2016). "In type 1 diabetes, blockade of DLL4 decreased T cell activation and increased T regulatory cell differentiation." (PMID 27933064, 2016).
uveal melanoma (2 papers, 2022). A melanoma derived from melanocytes of the uveal tract. "Of interest, among the NOTCH ligands, DLL4 is highly expressed in uveal melanoma cells, and it is the member whose expression is the most strongly associated with their metastatic ability." (PMID 35673577, 2022). "Furthermore, HES6 knockdown inhibited uveal melanoma cell migration induced by DLL4, one of the five NOTCH ligands." (PMID 35673577, 2022). "Consequently, DLL4 inhibition in uveal melanomas would be a logical approach since they have a strong propensity to metastasize via the hematogenous route." (PMID 35673577, 2022).
uveitis (2 papers, 2023 to 2025). An inflammatory process affecting a part of or the entire uvea. "The pathogenesis of uveitis involves elevated Notch1, DLL4, IL-17A, and RORγt, and decreased levels of miR-30b-5p." (PMID 40918405, 2025). "Additionally, our previous dual luciferase report gene expression assay showed that rno-miR-30b-5p specifically target Notch1 and DLL4, so miR-30b-5p could serve as a promising immunoregulatory approach for the treatment of uveitis." (PMID 40918405, 2025).
acute myeloid leukemia (1 paper, 2020). Acute myeloid leukemia (AML) is a group of neoplasms arising from precursor cells committed to the myeloid cell-line differentiation. "In acute myeloid leukemia, leukemic cells increased HUVEC tube formation through the activation of the VEGF and DLL4 pathway." (PMID 31616059, 2020).
airway hyperresponsiveness (1 paper, 2017). "In mice treated with DLL4 Ab, airway hyperresponsiveness was significantly aggravated." (PMID 28262821, 2017). "Additionally, eosinophilic airway infiltration and airway hyperresponsiveness were both ameliorated after Raw-DLL4 transfer." (PMID 28262821, 2017).
allergic conjunctivitis (1 paper, 2013). "Similarly, a study demonstrated that treatment with an anti-Dll4 antibody significantly augmented the development of murine experimental allergic conjunctivitis, as measured according to Th2 cytokine production and eosinophil infiltration." (PMID 23696838, 2013).
ameloblastoma (1 paper, 2020). The most common odontogenic tumor, arising from the epithelial component of the embryonic tooth and usually affecting the molar-ramus region of the mandible or maxilla. "Expression of NOTCH2 and NOTCH3 was associated with expression of the ligands JAG1, DLL1, and DLL4 in the ameloblastoma epithelium." (PMID 32155948, 2020). "We observed that NOTCH3, JAG1, DLL1, and DLL4 are also expressed within the ameloblastoma tumor mass." (PMID 32155948, 2020). "Some studies have reported the expression of NOTCH1, 2, and 3, as well as their ligands DLL1, DLL4, and JAG1, in all ameloblastomas analyzed." (PMID 32155948, 2020).
Autoimmunity (1 paper, 2017). The occurrence of an immune reaction against the organism's own cells or tissues. "Jag1 and Dll4 have opposite effects on sprouting angiogenesis and differential effects of Jag1 and Dll1,4 have been described on T cells proliferation and the regulation of T cell effector functions in autoimmunity." (PMID 28472949, 2017).
benign vascular tumor (1 paper, 2015). "Moreover, therapeutic inhibition of Dll4 signaling may face important safety limitations since chronic Dll4/Notch impairment was found to destabilize normal endothelium giving origin to the formation of benign vascular tumors." (PMID 26314892, 2015).
brain tumors (1 paper, 2021). "Blocking laminin expression in brain tumors leads to a decrease in expression of Notch ligand DLL4 at the protein level, decreasing the tumor volume, although this may primarily relate to the critical functions of DLL4 in the tumor vasculature in general, and endothelial cells in particular." (PMID 33430387, 2021).
cervical squamous cell carcinoma (1 paper, 2020). A squamous cell carcinoma arising from the cervical epithelium. "The expression level of DLL4 in patients with cervical squamous cell carcinoma was detected in the CC-RR and the CC-RS groups using Western blot analysis and Real-time PCR to further certify the relationship between DLL4 and CC radiosensitivity." (PMID 32742191, 2020).
chronic asthma (1 paper, 2019). An asthma that is characterized by the development of persistent airway inflammation and recurrent attacks of breathlessness and wheezing, which vary in severity and frequency. "In the aspect of allergic airway disease, we are awaiting this novel and promising DLL4 angiogenesis pathway being applied to clinical studies of chronic asthma." (PMID 31319491, 2019). "In this aspect, Tregs-elicited DLL4-Notch signals would be beneficial in preventing non-functional poor-perfused angiogenesis and ameliorating perfusion/ventilation abnormality as often seen in chronic asthma." (PMID 31319491, 2019).
colonic adenomas (1 paper, 2009). "The endothelium associated with colonic adenomas and adenocarcinomas (i.e., within two low-power fields of the tumour cells) was positive for Dll4 in 60–100% of vessels (identified by CD34 immunoreactivity in serial sections, data not shown)." (PMID 19844231, 2009). "The observation of Dll4 expression by neoplastic crypts and the association with goblet cell morphology in colon adenomas and adenocarcinomas is novel." (PMID 19844231, 2009).
colorectal adenocarcinoma (1 paper, 2025). The most common type of colorectal carcinoma. "Cis-activation of Notch2 by DLL4 has already been demonstrated in cultured colorectal adenocarcinoma cells." (PMID 39951484, 2025).
colorectal tumor (1 paper, 2013). "We found that endothelial DLL4 has the potential to induce colorectal tumor cell migration via NOTCH3 and Asef." (PMID 24244701, 2013). "Interestingly, it has been reported that DLL4 is highly expressed in blood vessels present in colorectal tumor tissues compared to those in normal colon mucosa." (PMID 24244701, 2013). "We therefore investigated whether expression of DLL4 on vascular endothelial cells stimulates the migration of colorectal tumor cells." (PMID 24244701, 2013).
congenital heart disease (1 paper, 2024). A heart disease that is present at birth. "Interestingly, SOX17 deficiency, a risk factor for the development of IPAH, HPAH and PAH associated with congenital heart disease, was reported to transcriptionally induce DLL4 and protect against vascular leakage." (PMID 38903104, 2024).
corticotropinomas (1 paper, 2017). "In concordance with Notch activation in this pituitary tumor type, an overexpression of the ligand Dll4 was found in corticotropinomas when compared to craniopharyngiomas." (PMID 28915655, 2017).
COVID-19 (1 paper, 2023). A disease caused by infection with severe acute respiratory syndrome coronavirus 2. "A Dll4-dependent signaling mechanism involving endothelial cells and macrophages in the COVID-19 heart is potentially related to HIF-1 signaling since these pathways are known to cross-talk through multiple mechanisms." (PMID 37830426, 2023).
Depression (1 paper, 2025). "Depression-associated pairs spanned Notch (JAG1-NOTCH2, DLL1-NOTCH3, DLL4-NOTCH3), ephrin (EFNA5-EPHA5, EFNA5-EPHA7, EFNA5-EPHA4), and extracellular matrix pathways (SLIT1-ROBO1, NTN1-DCC)." (PMID 40964296, 2025).
diabetic nephropathy (1 paper, 2024). "In individuals with diabetic nephropathy and db/db mice, there is an upregulation of Epsin1 and exosomal delta-like ligand 4 (DLL4) expression from tubular epithelial cells (TECs)." (PMID 38673935, 2024). "This indicates that Epsin1 may regulate communication between tubules and macrophages in diabetic nephropathy by facilitating the exosomal sorting of DLL4 and activating Notch1." (PMID 38673935, 2024).
dry eye (1 paper, 2016). "By using hypoxia-inducible factor-1 alpha conditional knockout (HIF-1α CKO) mice and a dry eye (DE) mouse model, we aimed to determine the role played by delta-like ligand 4 (Dll4)/Notch signaling and HIF-1α in the lymphangiogenesis of lacrimal glands (LGs)." (PMID 26828208, 2016).
encephalitis (1 paper, 2014). An acute inflammatory process affecting the brain parenchyma. "Furthermore, Dll4 expression in HFMD with encephalitis subjects correlated positively with total white blood cell (WBC) counts and total protein contents in cerebrospinal fluid (CSF) (p < 0.05)." (PMID 24939221, 2014). "However, we did not observe any significant differences in Notch ligand expression such as the Dll4 level between the uncomplicated HFMD group and the HFMD with encephalitis group." (PMID 24939221, 2014).
endometriosis (1 paper, 2018). The growth of functional endometrial tissue in anatomic sites outside the uterine body. "Dll4, a gene involved in the delta-notch pathways, participates in the decidualization failure of stromal cells from women with endometriosis." (PMID 30322386, 2018).
esophageal cancer (1 paper, 2022). A primary or metastatic malignant neoplasm involving the esophagus. "For example, stable knockdown of DLL4 decreases the esophageal cancer metastases by attenuating Akt phosphorylation." (PMID 36262998, 2022).
fibrosis (1 paper, 2021). the formation of excess fibrous connective tissue in an organ or tissue in a reparative or reactive process. "We previously published that DCs in BMT mice expressed lower levels of the Notch ligand DLL4 in response to herpesvirus infection, ultimately resulting in decreased Th1 skewing and increased Th17 skewing of lymphocytes, which contributed to post-BMT pneumonitis and fibrosis." (PMID 33491663, 2021).
Granuloma (1 paper, 2013). A compact, organized collection of mature mononuclear phagocytes, which may be but is not necessarily accompanied by accessory features such as necrosis. "Thus, the lower expression of CCL20 during mycobacterial challenge in either TLR9-deficient mice or anti-dll4–treated lungs might contribute to the observed decreased DC numbers during pulmonary granuloma formation." (PMID 23386849, 2013). "When Dll4 was specifically blocked in vivo using anti-Dll4 Ab during mycobacteria-induced pulmonary granuloma formation, Th17 cellular responses were significantly inhibited and larger granulomas were observed." (PMID 23386849, 2013). "More recently, our group showed the first analysis of cell-mediated Th17-related pulmonary mycobacterial Ag-elicited granuloma formation in TLR9−/− mice and defined a role for TLR9 in the induction of both Notch ligand Dll4 and Th17 expression using both in vivo and in vitro approaches." (PMID 23386849, 2013).
head and neck squamous cell carcinoma (1 paper, 2023). A squamous cell carcinoma that arises from any of the following anatomic sites: lip and oral cavity, nasal cavity, paranasal sinuses, pharynx, larynx, and salivary glands. "A recent study demonstrated that GD16-PTX-NP, a nanotherapy drug delivery system consisting of nanoparticles carrying paclitaxel conjugated with GD16 peptide, targeted Dll4 in human head and neck squamous cell carcinoma (HNSCC) FaDu xenograft mice." (PMID 37292204, 2023).
heart failure (1 paper, 2019). Inability of the heart to pump blood at an adequate rate to meet tissue metabolic requirements. "In cancer patients, administration of anti-Dll4 antibody caused heart failure in a subset of patients." (PMID 31191522, 2019).
hemangioblastoma (1 paper, 2024). "Subsequently, HIF-VEGF-VEGFR2, HIF-EPO, HIF-CAIX, HIF-SDF1β-CXCR4, HIF-EphB4/EphrinB2, and HIF-Notch/Dll4 are thought to play critical roles in angiogenesis in hemangioblastoma." (PMID 39850947, 2024).
infarction (1 paper, 2025). A localised pathological necrosis of tissue resulting from obstruction of the blood supply usually by a thrombus, an embolus, or vascular torsion. "DLL4 increased at 24 hr and 7 days of infarction after HT administration compared to control." (PMID 39850112, 2025).
influenza (1 paper, 2023). An acute viral infection of the respiratory tract, occurring in isolated cases, in epidemics, or in pandemics; it is caused by serologically different strains of viruses (influenzaviruses) designated A, B, and C, has a 3-day incubation period, and usually lasts for 3 to 10 days. "While influenza cases were primarily characterized by pro-inflammatory signaling and classical anti-viral response gene expression (e.g., BCL6, DLL4, GDF15, PTX3,HMGB2, and IL-8)." (PMID 36371548, 2023).
intestinal cancer (1 paper, 2017). "In addition to its angiogenic effect, Dll4/Notch seems to regulate the intestinal cancer cells through other mechanisms." (PMID 28086833, 2017).
intestinal tumor (1 paper, 2017). "We found that Dll4 is expressed near the Lgr5+ stem cells also in the intestinal tumors, therefore indicating a possible role of this ligand in the maintenance of also the tumor stem cells." (PMID 28086833, 2017). "The differences between the two types of Dll4 mutants in the expression of Lgr5 and Bmi1 markers in the small and large intestinal tumors were statistically significant." (PMID 28086833, 2017). "In summary, we show that Dll4 seems to be the ligand responsible, at least partially, for the previously reported Notch effects during intestinal tumor development." (PMID 28086833, 2017). "Therefore, given the observed reduction in the ApcMin/+ small and large intestinal tumor number in the Dll4 knock-out mice compared with the controls, we decided to analyse if Dll4 reduction was affecting the Lgr5+ and/or Bmi1+ stem cell expression in the tumors." (PMID 28086833, 2017).
invasive breast carcinoma (1 paper, 2018). A carcinoma that infiltrates the breast parenchyma. "The vessels in the invasive breast cancer seem to be seized with the Notch ligand Dll-4." (PMID 30111989, 2018).
Kaposi's sarcoma (1 paper, 2022). A malignant neoplasm characterized by a vascular proliferation which usually contains blunt endothelial cells. "In Kaposi sarcoma, JAG1- or delta-like canonical Notch ligand 4 (DLL4)-stimulated signaling results in the suppression of genes associated with the cell cycle in adjacent LECs, indicating a role for Notch signaling in inducing cellular quiescence in LECs." (PMID 36067135, 2022).
Li-Fraumeni syndrome (1 paper, 2016).
lung disease (1 paper, 2021). "To investigate the relevance of DLL4 in neonatal lung disease, we used a neonatal model of hyperoxic lung injury in vivo and in vitro." (PMID 33830085, 2021).
lymphopenia (1 paper, 2022). Reduction in the number of lymphocytes. "Normal MZB cells rely on the interaction of Notch2 receptors with Dll1 Notch ligands, although Dll4 Notch ligands are also expressed in the spleen and could become engaged in the setting of lymphopenia." (PMID 35579963, 2022).
metastatic cancer (1 paper, 2023). A carcinoma which has spread from the original site of growth to another anatomic site. "The cRGD-LNPs were also utilized to treat metastatic cancer by delivering delta-like ligand 4 (DLL4) siRNA." (PMID 38516300, 2023).
metastatic colorectal cancer (1 paper, 2017). "Other examples use either a bispecific DLL4/VEGF antibody (OMP-305B83) in metastatic colorectal cancer, combined with the chemotherapeutic agents FOLFIRI (NCT03035253); or in combination with the chemotherapeutics carboplatin and pemetrexed for lung cancer (NCT01189968)." (PMID 29170667, 2017).